TGFB1 (transforming growth factor beta 1)
Diseases named in the same sentence as TGFB1 in open-access papers (continued):
Sharing a sentence is not in itself a finding about the gene and the disease.
tumor (continued). "Also, TGFB1, ENG, B2M, HLA-F, SELPLG, and ITGB2 were significantly increased in tumor-associated macrophages, compared with those nontumor-associated macrophages." (PMID 36249427, 2022). "Besides TGFB1, the platelet-derived growth factor receptor PDGFRB was significantly upregulated in the F(h) ROIs, which agrees with increased CAFs and fibrosis in the corresponding tumor microenvironment." (PMID 36216799, 2022). "Accumulating evidence has suggested that TAMs can express a variety of immunosuppressive chemokines and factors which promote tumor cell proliferation and survival, including platelet-derived growth factor (PDGF), epithelial growth factor (EGF), and transforming growth factor beta 1 (TGFB1)." (PMID 36211379, 2022). "The decrease in APOE expression may promote tumor metastasis through NOTCH1, HIF1A, and TGFB1." (PMID 36428687, 2022). "Furthermore, Xing M demonstrated that activation of MAPK signaling pathway resulted in upregulation of tumor-promoting genes (e.g. VEGFA, MET, HIF1A, UPA, UPAR, TGFB1, and TSP1) as well as downregulation of tumor suppression and thyroid genes (e.g. TIMP3, SLC5A8, DAPK1, NIS, TSHR, and TPO)." (PMID 35600399, 2022). "In the TGFβ1 knockout 4T1 model, CPs did not affect tumor growth." (PMID 36209170, 2022). "Besides, transforming growth factor beta 1 (TGF-β1) can also be discharged from platelets, which represents the major source of peripheral circulating TGF-β1 that plays a multifaceted role in mediating tumor development." (PMID 36463115, 2022). "However, expression levels of FABP1, CD36, IRS1, THBS1, and TGFB1 did not significantly differ in various tumor stages." (PMID 36193307, 2022). "Similarly, the Wnt pathway has been shown to drive Tgfb1 and Bmp1 signaling and the promotion of a collagen-rich fibrotic phenotype that excludes T cell infiltration of the tumor." (PMID 36537914, 2022). "Compared to cells in tumor 3 that expressed increased epithelial markers like CDKN2A, CRB3, KRT13, and KRT6, tumor cells in metastatic LN exhibited high expression of mesenchymal markers like CDH3, ECM1, TGFB1, WARS, and VIM, indicating that tumor metastasis was related to EMT." (PMID 36569924, 2022). "In addition, we found that the expression levels of T-cell exhaustion-related genes including CD40, GRB2, MKI67, NFATC3, PRDM1, TCF7, and TGFB1 were significantly higher, while those of CXCR5 and TOX were significantly lower after tumor recurrence (all p < 0.05)." (PMID 34305618, 2021). "Importantly, such approach will be necessary to investigate TGFβ1 in regulating tumor progression when HCC cell lines are not available, such as in c-Met/β-Catenin induced mouse HCC." (PMID 33608500, 2021). "They established that tumor cells-secreted IL1 promoted an inflammatory-like phenotype in CAFs via JAK/STAT signaling pathway, and that this event could be antagonized by the exposure of these inflammatory CAFs to TGFβ1." (PMID 34183054, 2021). "Finally, we measured the amounts of Tgfβ1 cytokine in the lungs of tumor-bearing mice and compared them with non-injected (naïve) mice." (PMID 34868988, 2021). "Based on our hypothesis that RAC1B is a tumor suppressor gene, we nevertheless speculated that induction of endogenous TGFB1 may serve anti- rather than protumorigenic functions." (PMID 33260366, 2020). "Based on tumor purity, we ascertained that most cytokines are secreted by TAMs and M2 macrophages, and marker sets have significant correlations with CDH11 in STAD, with examples including CCL-2, TGFB1, CXCL12, and MPP2 of TAMs and IL-10, IL1R1, CD163, and MRC1 of M2 phenotype (P < 0.0001)." (PMID 32685527, 2020). "In addition, multiple tumor cell injections in the mouse liver metastasis models were found to increase the number of CD4+ CD25 + Treg cells and the expression of cytokines IL-10 and TGFβ-1." (PMID 32408477, 2020).
tumor (continued). "Next, to test whether the normalization of tumor blood vessels and ECM can improve intratumoral nanomedicine delivery, we treated tumor‐bearing mice with combined DC101 and anti‐TGFβ1 antibody and measured the distribution of nanoparticles within the tumor interstitium." (PMID 30886813, 2019). "In addition, higher levels of TGFβ1 were detected in the tumor tissues, as compared to nontumor adjacent tissues." (PMID 31450767, 2019). "Moreover, recent studies have suggested that TGFβ1 signaling may be involved in the epigenetic regulation of EMT and DNA methylation maintenance during tumor progression." (PMID 31109321, 2019). "To reveal the contribution of the tumor-platelet interaction to the proliferation, transmigration, and invasion of C8161 cells, we measured the levels of platelet-derived growth factor PDGF-BB and transforming growth factor TGFβ-1 in the supernatants of C8161 cells co-cultured with platelets." (PMID 31208371, 2019). "With S-MpMs being poorly enriched in T cells, TGFB1 should not be derived from suppressive immune T cells, but it might be transcribed directly by the tumour cells, consistently with the mesenchymal nature of S-MpMs." (PMID 30510965, 2018). "However, it remains unclear how TGFβ1 promotes NSCLC cells to acquire stem-like properties and accelerate tumor metastasis." (PMID 29995950, 2018). "Similarly, anti-HCC miR148a and miR125b exert inhibitory effects on epithelial mesenchymal transition (EMT) and CSC-like phenotypes by targeting TGFβ1, which is a potent stimulator for EMT in the tumor microenvironment and induces the transformation of liver stem cells into CSCs in HCC." (PMID 30224923, 2018). "Alternatively, the presence of TGFβ in both the periphery as well as the tumor of αPD-L1-treated animals may prevent CD8+ T cell activation upon vaccination, which M7824 can overcome as it both sequesters plasma TGFβ1 and prevents TGFβ-induced signaling." (PMID 29721396, 2018). "Although Twist was active in all tumours, its regulation was not controlled by TGFβ1." (PMID 29976164, 2018). "The tumor microenvironment is a site where chemokines and cytokines, such as VEGF, urokinase plasminogen activator (uPA), IL-8, transforming growth factor beta-1 (TGF-b1), and monocyte chemotactic protein-1, are abundantly secreted, and these molecules may induce the homing of MSCs." (PMID 29760719, 2018). "In the non-responding tumor, enrichment of the pathways 'loss of function of SMAD4 in cancer' and 'SMAD4 MH2 domain mutants in cancer' indicates that the non-responder tumor shows impaired TGFB1-related transcription initiation, which corresponds to the observed (non-responder) phenotype." (PMID 28594404, 2017). "Indeed, TGFβ1 and IL4 act as Id3 transcriptional repressors, which results in E-protein- and GATA-3-mediated activation of the IL9 gene transcription and even in enhanced anti-tumor response of the T cells in a melanoma mouse model." (PMID 28122577, 2017). "Interestingly, proliferation of both tumor cell lines was significantly reduced when cultured in CM of IFNγ- and TNFα-activated microglia (p < 0.001, ratios 0.51 and 0.49), but not by TGFβ1-treated microglial CM (ratios 0.98 and 1.05)." (PMID 28008153, 2017). "Although the immunosuppressive activities of TGFβ1 in the tumor microenvironment have been accepted as one rational explanation, this does not explain the role that TGFβ1 plays within tumor cells lacking functional Smad4 to promote proliferation, metastasis, and apoptotic resistance." (PMID 28649369, 2017). "To clarify whether Pitx2 is a tumor suppressor in the downstream of TGF-β-Smad4 pathway in PDAC, we firstly detected the Pitx2 levels with or without inhibitors against ERK1/2 (PD98059), p38 (SB202190), TGFβ1-Smads (SB431542), and JNK (SP600125)." (PMID 26848620, 2016).
tumor (continued). "Interestingly, the role of the vascular niche in maintaining tumour cell dormancy is not so clear-cut, and that sprouting neovasculature can promote metastatic outgrowth as a result of active TGFβ1 and periostin secreted from endothelial tip cells." (PMID 27782035, 2016). "Moreover, tumor cells that ultimately escape SMAD-dependent growth inhibitory signals from TGFβ1 do not necessarily become totally unresponsive to this cytokine; rather, many tumors evolve to shift TGFβ1 signals along pro-oncogenic pathways." (PMID 27589814, 2016). "However, deletion of a number of key TGFβ signaling components (e.g., TGFβ1, TGFBR1, SMAD2/3, and SMAD4) alone in the ovary does not induce tumor formation, challenging TGFβ signaling as essential tumor suppressor in the ovary." (PMID 27344183, 2016). "Of note, while TGFB1, a master regulator of the malignant phenotype, appeared to be mostly up-regulated in the tumour, its activators THBS1, FN1 and ITGA4 were strongly induced in tumor cells and ECs, highlighting a concerted molecular interaction to regulate cellular activity." (PMID 27049916, 2016). "Thus treatment of G-2 cells with the potent EMT-inducer TGFβ1 induced an enhanced plasticity of the tumor cells rather than a complete EMT, as evidenced by the absence of changes in the levels of phenotypic markers." (PMID 25886487, 2015). "Higher TGFB1 mRNA expression levels were observed in tumours compared with adjacent normal tissues and seemly in tumours from lymph node-positive patients compared with tumours from lymph node-negative patients." (PMID 26703884, 2015). "However, the tumor would not be sensitive to TGFβ-1 mediated growth inhibition with the development of tumor." (PMID 26003220, 2015). "Importantly, in the multivariate analysis, when adjusted to tumor size, lymph node positivity, SBR grade, ER and PR status, TGFβ1 expression was still an independent predictor for distant metastasis (HR = 2.56, 95 % CI: 1.5 to 4.3, p < 0.0001) and death (HR = 2.06; 95 % CI: 1.13 to 3.75, p = 0.018)." (PMID 26040677, 2015). "Seemly lower TGFB1 mRNA levels were observed in the tumours from regional lymph node-negative patients and in the triple-negative tumours, and lower TGFBR1 mRNA levels were observed in HER2 negative tumours, though the corresponding p-values did not survive Bonferroni correction." (PMID 26703884, 2015). "Identification of the signaling pathways and mechanisms regulating TGFβ1-induced decorin down-regulation in CAF/MF in vitro and in vivo will provide a rationale for new therapeutic options aimed to neutralize the oncogenic role of TGFβ1 as a repressor of the decorin tumor suppressive functions." (PMID 25526025, 2014). "Interestingly, myofibroblasts generated using soluble TGFβ1 were not pro-angiogenic or tumor-promoting, suggesting that exosomal TGFβ1 is required for the formation of tumor-promoting stroma." (PMID 25566500, 2014). "Moreover, TGFβ1 in cancerous or paracancerous liver tissue had no connection with either tumor vessel invasion or lymph metastasis." (PMID 23251252, 2013). "Double immunofluorescence analysis showed that a subpopulation of CD30+ cells overexpressed TGFβ1 and MMP9, suggesting that CD30+/TGFβ1+ and CD30+/MMP9+ cells may potentiate a metastatic environment that allows CD30+ HL tumor cells to exit the local tumor microenvironment." (PMID 23988031, 2013). "Therefore increased expression of TGFβ1 in cancerous tissues may trigger the process of EMT promoting invasion and tumor progression." (PMID 22844446, 2012). "Thus, it appears that TGFβ1-mediated EMT is a tumor cell autonomous effect, but metastasis induction may involve changes in the tumor microenvironment or altered TGFβ1 signaling in tumor cells." (PMID 23326666, 2012). "Therefore, losartan effectively reduced the expression, activation and signaling of TGFβ1 during tumor progression in the absence of host SPARC." (PMID 22348081, 2012).
tumor (continued). "Of the one hundred and twenty two patients where the information was available, the hormone receptor negative tumor bearing subjects were characterized by a strikingly lower frequency of TGFB1*CC genotype compared to the hormone receptor positive group (8 of 64 vs 10 of 40)." (PMID 21829601, 2011). "TGFβ1 has been reported to up-regulate IL-8 and we detected increased IL-8 secretion in response to TGFβ1 in non-mineralized cultures, but surprisingly not in mineralized tumor models." (PMID 20107512, 2010). "Collectively, TGFβ1+ Treg may mediate CD8+ T cell dysfunction through these ligand‐receptor interactions, accelerating T cell exhaustion and apoptosis, thereby fostering a profoundly immunosuppressive tumor microenvironment that ultimately drives CRC immune evasion and malignant progression." (PMID 40891683, 2025). "If this hypothesis is correct, one could predict that co-expression of an anti-apoptotic mediator, such as Mcl-1, would rescue TGFβ1 dependent tumor inhibition phenotype, i.e., overexpression of TGFβ1 would not be able to suppress tumor development induced by c-Myc and Mcl-1 oncogenes in the liver." (PMID 33608500, 2021). "The present study investigated whether the TGFβ1 level in CAFs of resected tumors of patients with SCLC may be an indicator of prognosis, and furthermore the effect of this level on the proliferation and radiotherapeutic sensitivity of tumor cells and tumor immune status." (PMID 34095135, 2021). "Finally, we demonstrate that combined blockade of signalling ligands PD-L1 and TGFβ1 together with inhibition of indoleamine 2,3-dioxygenase 1 (IDO1) was able to reverse, in part, the suppressive effects of peritumoral CD90+CD73+ cells on tumor-infiltrating lymphocytes (TILs)." (PMID 34740105, 2021). "Moreover, the tumor-infiltrating lymphocytes from tumor-bearing mice were analyzed by flow cytometry, and showed that TIPE2 could promote T cell activation to exert an anti-tumor effect possibly through activation of DCs in a TGFβ1 dependent manner." (PMID 34249724, 2021). "Together, these NRP-1 findings in conjunction with studies highlighting the role of TGFβ signaling in EndMT, helped us postulate that NRP-1 could be playing a previously unrecognized regulatory role in TGFβ1-induced EndMT and potentially contributes towards tumor fibrosis." (PMID 27542226, 2016). "However, upon attenuation of this antiproliferative signal, tumor cells often secrete great amounts of TGFβ1 which promote cell invasion, epithelial-to-mesenchymal transition (EMT) metastasis, and angiogenesis which collectively establish a growth-supportive tumor microenvironment." (PMID 27144026, 2016). "Although this study suggests that TGFβ1 inhibition could be a tool to prevent or treat EPS, direct and chronic inhibition of systemic TGFβ1 activity is probably not desirable in humans given the important role of TGFβ1 in immune regulation and tumor suppression." (PMID 25384022, 2014). "We showed that TGFβ2 expression but not TGFβ1 or TGFβ3 expression is preferentially elevated TNBC cell lines, patient serum and tumour samples." (PMID 38299307, 2024). "In the tumour immune microenvironment, reduced interaction between myeloid‐derived TGFB1 and TGFBR1 in tumour focus No. 2 contributed to tumourigenesis and increased heterogeneity." (PMID 38426403, 2024). "However, in this study, no overall correlation between ITGAV and TGFβ1 could be derived as the expression of TGFβ1 followed a classical tumour progressive trend (was higher in primary tumours versus normal kidney tissues and was also high in metastatic versus primary tumours." (PMID 37174052, 2023). "Interestingly, the addition of anti-CTLA-4 with either TGFβ1 or TGFβ3 inhibition, but not pan-TGFβ inhibition, had an even stronger effect in prolonging overall survival compared to isoform-specific TGFβ blockade alone but did not significantly affect tumor growth." (PMID 34789823, 2021).
tumor (continued). "Many studies have used HDAC inhibitors to block lung fibrotic process and tumor growth, and SAHA, a nonselective HDAC Class I and II inhibitor, has been reported to have the ability to inhibit the differentiation of TGFβ1-induced myofibroblasts." (PMID 32943605, 2020). "To confirm the high expression of HIF-1α and TGF-β in vivo, we analyzed data of The Cancer Genome Atlas (TCGA) HCC cohorts and found that TGFB1 and HIF1A expression were significantly overexpressed in 371 tumor specimens compared with 50 non-tumor tissues." (PMID 31819036, 2019). "This was dependent on accumulation of M7824 in the tumor, as M7824mut decreased TGFβ1 levels in the plasma but did not bind to TME-expressed PD-L1 and did not decrease TGFβ-dependent signaling in the TME." (PMID 29721396, 2018). "Among them, IL‐6 and TGFB1 were upregulated in the noncancer, tumor‐adjacent tissue of AAM, but for EAM, IL‐6 expression was increased in PCa tissue and TGFB1 was not differentially expressed." (PMID 29741809, 2018). "We were disappointed that there is no alterations in cell proliferation and expression of tumor progression-related genes including HIF1A, TGFβ1 and VEGF at RNA levels but decrease of trans-well cell migration assays in HCC cells PLC5, SNU449 and Huh7." (PMID 29568350, 2018). "Expression of EIF3C did not alter proliferation and expression of other tumor progressive genes such as HIF1A, TGFβ1 and VEGF, but reduced cell migration in HCC cells." (PMID 29568350, 2018). "The roles TGFβ1 and EMT in cancer progression have been investigated by many tumor biologists, but the mechanism of TGFβ1-induced EMT is not completely understood." (PMID 28404892, 2017). "In partial discordance with these data, we have demonstrated that OS CSC do not secrete TGFβ1 that is rather secreted by the mesenchymal counterpart and considerably increases when MSC are adjacent to the tumor component." (PMID 27851822, 2016). "We first evaluated Tgfb1 gene induction in tumor tissue after CDDP-Eri treatment and observed that chemotherapy-induced Tgfb1 expression was lower, but not completely lost, in Tgfb1–/– compared with WT 4T1 tumor tissue." (PMID 40590231, 2025). "Moreover, Tumor IMmune Estimation Resource (TIMER) analysis of TCGA-LIHC dataset revealed a negative correlation between the expression of TREM2 and TGFB1 and the infiltration levels of naive CD8+ T cells." (PMID 39838454, 2025). "Additionally, Tgfβ1 activates non-canonical pathways such as PI3K/AKT and MAPK, which are increasingly recognized for their roles in tumor progression." (PMID 41360769, 2025). "In our study, reduced interaction between myeloid‐derived TGFB1 and TGFBR1 in tumour foci No. 2 contributed to tumourigenesis and increased heterogeneity, which was support by the spatial‐geneset‐score and nichenet analysis, quantitate PCR and cell proliferation validation results." (PMID 38426403, 2024). "Clustering IL10, TGFβ1 and FOXP3 may also provide a better understanding of the contribution of the regulatory subsets to the systemic immunodeficiency and lack of tumour clearance observed in CLL patients." (PMID 36973425, 2023). "Moreover, the lack of Tgfβ1 in cancer cells, which leads to the activate the cytotoxic function of CD8 T cells in the TME, failed to affect Treg homeostasis in the tumor." (PMID 34711823, 2021). "Similarly, in vivo, subcutaneous tumor xenografts established from co-implantation of WT KYSE-450 and MRC-5 cells pretreated with TGFβ1 and PLAU grew faster than the controls without PLAU pretreatment, and this effect was also inhibited by IPR-803." (PMID 33574243, 2021).